PGR (progesterone receptor)
Diseases named in the same sentence as PGR in open-access papers (continued):
Sharing a sentence is not in itself a finding about the gene and the disease.
breast tumors (232 papers, 1992 to 2026). "Instead, the analysis of breast tumor of a neoadjuvant cohort revealed TRIP6 mRNA expression level associations with positive progesterone receptor expression status and premenopausal status." (PMID 36833223, 2023). "Mice models of BRCA1-deficient breast tumours have shown increased progesterone receptor expression in both the breast tumours and the adjacent benign tissue, and that mammary tumorigenesis can be prevented with progesterone inhibition." (PMID 30915162, 2019). "Most breast tumors are estrogen receptor and progesterone receptor positive and are associated with better overall survival." (PMID 29739401, 2018). "The BRCAness phenotype is related to sporadic TNBC, which shares clinical and histological characteristics with germline BRCA1-mutated breast tumours (young age, high grade and negativity for the ER, PgR and HER2)." (PMID 29259228, 2017). "The degree of nuclear contour irregularity observed in breast tumors correlates with loss of progesterone receptor expression and with disease progression." (PMID 23405182, 2013). "BRCA1-associated breast tumours are mostly high-grade invasive ductal carcinomas (IDCs) that lack expression of estrogen receptor (ER), progesterone receptor (PR) and ERRB2/HER2, which is referred to as ‘triple-negative’ breast cancer." (PMID 19904273, 2009). "The purpose of the present study was to examine expression patterns of Bag-1 in a large cohort of breast tumors and to assess the association with Bcl-2, estrogen receptor, progesterone receptor and Her2/neu, and other clinical/pathological variables." (PMID 18430249, 2008). "In this study, we measured hK6 and hK10 protein levels in breast tumour cytosols and found that they were positively correlated with each other, but negatively associated with ER and PgR." (PMID 12087468, 2002). "The data presented suggest that different agents used to treat estrogen- and/or progesterone-receptor-positive breast tumors may be associated with different patterns of genitourinary symptoms." (PMID 41590219, 2025). "In luminal breast tumors, characterized by estrogen receptor (ER) and/or progesterone receptor (PR) expression, mutations in enhancers and promoters of hormone-responsive genes, such as FOXA1 and ESR1, can disrupt hormone signaling, leading to endocrine therapy resistance." (PMID 41011238, 2025). "In summary, our study represents the first investigation showing that high hK10 protein levels are associated with low ER and PgR levels in breast tumours and that high hK10 levels in tumour tissue are independent predictors of poor response to tamoxifen therapy." (PMID 12087468, 2002). "Thus, type of lipoprotein subfractions may be associated with several breast tumor characteristics, and not only PgR expression." (PMID 26970778, 2016). "This analysis revealed distinct expression patterns among glioma, endometrium, ovary, lung and breast tumors, underscoring the variability of PGR expression across cancer types." (PMID 41439468, 2026). "BC is widely recognized as a hormone-dependent disease, as approximately 75% of breast tumors express estrogen receptors (ER) and progesterone receptors (PgR)." (PMID 40593140, 2025). "In fact, they found that subtypes of the same tumor type, for example, in breast tumors, estrogen receptor (ER), progesterone receptor (PR), and HER2 subtypes each had a distinct microbiome." (PMID 39981299, 2024).
breast tumors (continued). "Breast tumors are commonly classified into four subtypes based on the expression of estrogen receptor (ER), progesterone receptor (PR), and human epidermal growth factor receptor 2 (HER2/ERBB2)." (PMID 38468288, 2024). "The classification of breast tumors is based on the status of ER and further prognostic biomarkers, including progesterone receptor (PR), human epidermal growth factor receptor (HER2), and the proliferation marker Ki-67." (PMID 38937754, 2024). "The expression status of estrogen receptor (ER) or progesterone receptor (PR) in at least 1 % in breast tumor cells is collectively termed hormone receptor-positive (HR+)." (PMID 39117925, 2024). "Breast tumors are traditionally classified into distinct molecular groups based on their estrogen receptor (ER), progesterone receptor (PR), and human epidermal growth factor receptor 2 (HER2) expression patterns." (PMID 38913216, 2024). "Several studies revealed that PGR plays a noteworthy role in chemoresistance of endometrial tumors and breast tumors." (PMID 38424455, 2024). "Accordingly, breast tumors are initially classified by immunohistochemistry (IHC) based on the expression of estrogen receptor (ER), progesterone receptor (PR), human epithelial growth factor receptor 2 (HER2) and the proliferative marker Ki-673." (PMID 38042915, 2023). "Hormone receptor status: Hormone receptor status, including estrogen receptor (ER) and progesterone receptor (PR) expression, differs between ductal and lobular breast tumors." (PMID 37564937, 2023). "Around 75% of all breast tumors express the estrogen receptor (ER) and/or the progesterone receptor (PgR) and are considered as hormone receptor-positive (HR) tumors." (PMID 37293258, 2023). "The observation of higher PGR expression in cBLMTs and canine tumors than in human breast tumors is supported by other canine and human studies." (PMID 37034591, 2023). "Understanding how breast tumors adapt to evade hormonal therapies, including changes in estrogen and progesterone receptor expression, is essential for developing strategies to combat resistance." (PMID 38116321, 2023). "One retrospective analysis of 993 intraindividual tissue samples from primary breast tumors and relapses found alterations in estrogen receptor (ER), progesterone receptor (PR), and HER2 status in 32%, 41%, and 15% of patients, respectively." (PMID 35545724, 2022). "Breast tumors are historically classified based on specific molecular signatures such as Progesterone Receptor (PR), Estrogen Receptor (ER) and Human Epidermal Growth Factor Receptor 2 (HER2) by classical immunohistochemical assay." (PMID 35788171, 2022). "Estrogen receptor (ER) and progesterone receptor (PR)-positive breast tumors were most common within our study population overall (n = 16/33, 48.5%,)." (PMID 35743613, 2022). "Luminal B breast tumors are characterized by a lower expression of estrogen receptor, and low expression of progesterone receptor." (PMID 35432489, 2022). "Owing to a high prevalence of ER(+)PgR(−) phenotype among breast tumors recurring after tamoxifen treatment, PGR methylation status was proposed as a predictive marker for tamoxifen insensitivity." (PMID 34638241, 2021). "Endocrine therapy is the first line treatment in estrogen receptor (ER) and progesterone receptor (PR) positive breast tumors, whereas chemotherapy represents the recommended treatment in patients with the aggressive triple-negative breast cancer (TNBC)." (PMID 33562737, 2021). "Despite the global consensus, many studies suggest other thresholds for determining the survival outcomes of patients with breast tumors expressing low ER or PgR levels." (PMID 34638491, 2021). "Encouraged by these promising preclinical studies, we tried to use FENP to image ER and PgR-positive breast tumors in women and were most surprised to find that there was little tumor uptake at all." (PMID 32718075, 2020).
breast tumors (continued). "First, only grade 2 breast tumors that demonstrated positive ER and PgR status and Ki67 > 30% by immunohistochemical assays were assessed." (PMID 32514046, 2020). "Currently, breast tumor classification is primarily based on histopathologic features and the expression of estrogen receptor (ER), progesterone receptor (PR) and human epidermal growth factor receptor 2 (HER2)." (PMID 32241272, 2020). "All breast tumors are characterized based on receptor status (estrogen receptor, ER; progesterone receptor, PR; human epidermal growth factor-2, HER2) and a panel of genes contributing to predictive and prognostic indices." (PMID 31060575, 2019). "Observed changes in PSA and PGR expression in prostate and breast tumors as markers of AR and ERα signaling, respectively, reflected the natural tumor heterogeneity observed clinically for each tumor type examined." (PMID 30117261, 2018). "In the current study, we show that our results are in line with these findings in clinical material and associations between nuclear raptor localization, low tumor grade, and ERα/PgR status of breast tumors." (PMID 29128895, 2018). "Breast tumor subtypes are defined based on the expression of three primary identifiers: estrogen receptor (ER), progesterone receptor (PR) and human epidermal growth factor receptor 2 (HER2)." (PMID 30647871, 2018). "In the present study, we used proteomics and miRNA profiling techniques to characterize a set of 102 either estrogen receptor-positive (ER+)/progesterone receptor-positive (PR+) or triple-negative formalin-fixed, paraffin-embedded breast tumors." (PMID 28855612, 2017). "Consistently with this model, AR and FOXA1 mRNA expression positively correlated with percentage of ER and PgR expressing cells in our cohort of breast tumours, but only FOXA1 mRNA expression negatively correlated with miR-9-5p expression." (PMID 28345661, 2017). "Breast tumors that are ER or PgR-positive are much more likely to respond to hormone therapy than tumors that are negative." (PMID 28122498, 2017). "Analyses by breast tumor subtype revealed potential heterogeneity for rs2288378, representing the four high-LD IGF1 SNPs, decreasing risk of only ER+ and/or PgR+/HER2− tumors by approximately 45% among East Asian women." (PMID 27376028, 2016). "The use of additional breast tumor markers, such as estrogen receptor (ER), progesterone receptor (PR), and human epidermal growth factor receptor 2 (Her2/neu), can be used for confirmation of the source of the tumor." (PMID 25883818, 2015). "ER-/PgR+ breast tumors have different tumor and patient characteristics, when compared to tumors expressing both ER and PgR (ER+/PgR+) as well as those without expression of either HR (ER-/PgR-)." (PMID 26161666, 2015). "Increasing number of IHC molecules have been identified to play critical roles in breast tumor subtyping, among which estrogen receptor (ER), progesterone receptor (PR) and human epidermal growth factor receptor 2 (HER2) are the most commonly used." (PMID 26404658, 2015). "A proposed molecular profile approach for breast tumor classification defines distinct molecular subtypes of the disease based on differences in the expression patterns of estrogen receptor (ER), progesterone receptor (PR) and HER2 (ERBB2)." (PMID 25743390, 2015). "According to miRNA profile, the characteristic tendency of TNBCs to cluster differentially compared to other breast tumor groups expressing ER, PgR or HER2, was reported in a set of normal, DCIS and invasive BC cases." (PMID 25406994, 2014). "The dysfunctional ERs in the ER+PgR− phenotype showed slower rates of tissue invasion, suggesting that ligand binding to functional breast tumor ERs, beside promoting the PgR expression, possibly also promotes tumor transition to the invasive phase." (PMID 24917206, 2014).
breast tumors (continued). "When considering age of patients and the relative rate of tissue invasions, breast tumors with the dysfunctional ER+PgR− phenotype progressed faster in younger patients and 33% slower than expected in older patients." (PMID 24917206, 2014). "Approximately 75% to 80% of human breast tumors express hormone receptors (HRs), the estrogen receptor (ER), and/or the progesterone receptor (PgR)." (PMID 24387226, 2014). "In other words, ligand binding to functional ERs is a physiologic prerequisite for PgR expression in breast tumor cells." (PMID 24917206, 2014). "Our question was the identification of relationship between the results of sample clustering and the clinico-pathological data (ER, PgR and Her2), which are still considered the gold standard for diagnosis and prognosis of breast tumors." (PMID 25406994, 2014). "Brain metastases as the first site of distant recurrence were associated most frequently with the basal subtype and primary tumor expression of nestin, prominin-1, or CK-5, and, on the other hand, they were rare when the breast tumor expressed ER or PgR." (PMID 21914172, 2011). "Using quantitative AQUA IHC technology we found that 4ICD potentiated PgR expression in primary breast tumors and the highest levels of PgR expression required coexpression of ERα and the 4ICD coactivator." (PMID 20550710, 2010). "Reintroduction of wild-type HER4 but not the γ-secretase processing mutant HER4V673I into the TamR cell line restored PgR expression indicating that 4ICD is an essential PgR coactivator in breast tumor cells." (PMID 20550710, 2010). "We used a sophisticated automated quantitative analysis (AQUA) algorithm to measure levels of ER, PgR, and nuclear or cytoplasmic 4ICD in primary human breast tumors by IHC." (PMID 20550710, 2010). "We next determined the impact of HER4 expression on estrogen stimulated expression of endogenous PgR in the ERα-positive MCF-7 breast tumor cell line." (PMID 20550710, 2010). "Suppression of HER4/4ICD expression in the MCF-7 breast tumor cell line completely eliminated estrogen stimulated expression of PgR." (PMID 20550710, 2010). "It has also been observed that breast tumors expressing the progesterone receptor have higher observed Src activity." (PMID 18167534, 2008). "Estrogen receptor alpha (ERα), progesterone receptor (PR) and proliferative activity (Ki-67) levels were measured in paraffin-embedded biopsies of breast tumors by immunohistochemistry." (PMID 16859517, 2006). "An additional indicator of estrogen signaling activity in breast tumors is the higher expression of known estrogen-inducible targets, such as progesterone receptor (PR)." (PMID 16606439, 2006). "We show that, as a group, E2-regulated genes from our preclinical models were co-expressed with ERα in a panel of ERα+ breast tumor mRNA profiles, when corrections were made for patient age, as well as with progesterone receptor." (PMID 16606439, 2006). "The proportion of oestrogen and progesterone receptor positive breast tumours has been found to increase with age, possibly making a potential promoting effect of pregnancy oestrogens more pronounced, regardless of birth order." (PMID 15597097, 2005). "AR immunoreactivity was present in the nuclei of breast tumour cells and was correlated with oestrogen receptor (ER; P < 0.05) and progesterone receptor (PR; P < 0.01) status." (PMID 9703283, 1998). "This study aimed to investigate the effect of tamoxifen on breast tumour levels of oestrogen and progesterone receptor (ER and PR) and proliferation as defined by the Ki67 antibody." (PMID 8439511, 1993). "In this study, the variability in the profile of ER isoforms and its relation to progesterone receptor (PgR) levels in breast tumours has been studied." (PMID 1457348, 1992).
breast tumors (continued). "The histological classification of breast tumors has occurred based on specific receptor expressions such as the estrogen receptor (ER), the progesterone receptor (PgR) and the human epidermal growth factor receptor 2 (HER2) in addition to the percentage of the proliferating index (Ki67)." (PMID 36983016, 2023). "Breast tumors can be divided into subtypes using two parameters: (I) At the molecular level based on the protein expression of three receptors: estrogen receptor (ER), progesterone receptor (PR) and human epidermal growth factor receptor 2 (HER2)." (PMID 36224576, 2022). "HCMV DNA and/or proteins in breast tumors have been associated with higher tumor grade, invasive breast cancer, and negative expression of the estrogen receptor-1 (ER), progesterone receptor (PR) and human epidermal growth factor receptor 2 (HER2)." (PMID 35267456, 2022). "Therefore, there is a strong need to analyze the entire spectrum of ER and PgR expression levels for breast tumors." (PMID 34638491, 2021). "In addition, for prognostic and predictive purposes, all invasive breast tumours are tested for expression of the oestrogen receptor (ER) and progesterone receptor (PR) as well as for overexpression of the human epidermal growth factor receptor 2 (HER2)." (PMID 33640523, 2021). "Interestingly, one study reported a higher incidence of DNA methylation in PGR promoter in HER2-amplified/overexpressing cases, pointing to the role of methylation in the pathogenesis of ER(+)/PgR(−)/HER2(+) breast tumors." (PMID 34638241, 2021). "However, breast tumors are presently stratified on the basis of ER, progesterone receptor (PR), HER2 and the proliferation marker Ki-67 into the luminal A, luminal B, HER2-positive and triple-negative subtypes." (PMID 33906694, 2021). "According to available information, 91.5% (54/59) of breast tumors were estrogen receptor (ER) positive and 67.8% (40/59) of tumors were progesterone receptor (PR) positive, whereas HER2 (human epidermal growth factor receptor 2) was overexpressed in 18.6% (11/59) of tumors." (PMID 33925588, 2021). "High anillin expression was associated with more aggressive estrogen and progesterone receptor-deficient (ER-, PR-) breast tumors but appeared to be independent of the human epidermal growth factor receptor 2 (HER2) status." (PMID 31910867, 2020). "The molecular features typically used for breast tumor subtyping include expression of the estrogen receptor (ER) and the progesterone receptor (PR), activation of human epidermal growth factor receptor 2 (HER2/neu, encoded by ERBB2), and/or the presence of BRCA1/2 mutations." (PMID 33352803, 2020). "PGR expression was mostly restricted to ER+ breast tumors (last panel, yellow and blue)." (PMID 33291647, 2020). "Breast tumors are subdivided into different categories based on the receptors expressed in the cells: estrogen receptor (ER)- or progesterone receptor (PR)- positive, human epidermal growth factor receptor 2 (HER2) positive, and triple negative breast tumors (ER-/PR-/HER2-)." (PMID 30678106, 2019). "Tumors of the breast in AYAs often lack expression of therapeutic targets, such as estrogen receptor (ER), progesterone receptor (PgR), and human epidermal growth factor receptor 2 (HER2) oncoprotein (i.e., they are of the triple-negative subtype), and have a poor prognosis." (PMID 29464067, 2018). "The progesterone receptor also functions as a nuclear transcription factor controlling a large number of genes; however, it is controlled and induced by ER signaling in normal reproductive tissue as well as in breast tumors." (PMID 28430646, 2017). "It has long been observed that the ERα and/or PgR status of the metastatic tissue may be discordant with that of the primary tumour, with ERα+ but PgR− breast tumours comprising the poorer-prognosis Luminal B subtype." (PMID 27189371, 2016).